MAG (myelin associated glycoprotein)
Diseases named in the same sentence as MAG in open-access papers (continued):
Sharing a sentence is not in itself a finding about the gene and the disease.
amyotrophic lateral sclerosis (1 paper, 2024). Amyotrophic lateral sclerosis (ALS) is a neurodegenerative disease characterized by progressive muscular paralysis reflecting degeneration of motor neurons in the primary motor cortex, corticospinal tracts, brainstem and spinal cord. "However, some studies suggest an association between this condition and motor neuropathy, and at least one study reported a patient with amyotrophic lateral sclerosis (ALS) and antibodies to SGPG which can cross-react with MAG." (PMID 38912071, 2024).
Arthritis (1 paper, 2015). Inflammation of a joint. "We propose that MAG-EPA is able to reduce arthritis severity in a CFA rat model." (PMID 26022389, 2015).
axonal neuropathy (1 paper, 2019). Any nerve disorder affecting the axon of a nerve. "In vivo, MAG prevents the appearance of sensitive axonal neuropathy and neuromuscular dysfunction induced by oxaliplatin without affecting its antitumor action." (PMID 31741707, 2019). "In conclusion, MAG prevents the appearance of sensitive axonal neuropathy and neuromuscular disorders induced by oxaliplatin without affecting its antitumor activity." (PMID 31741707, 2019).
Cerebral ischemia (1 paper, 2022). Restriction of arterial blood supply to the brain associated with insufficient oxygenation to support the metabolic requirements of the tissue. "The inhibition of neurite outgrowth and neuronal regeneration by the MAG or Nogo-A signaling cascades block the functional recovery after the suffering of cerebral ischemia." (PMID 36678774, 2022).
chorioamnionitis (1 paper, 2024). A morphologic finding indicating inflammation of the fetal sac membranes. "In the changes we observed, in addition to disrupted neuronal maturation, we found that chorioamnionitis also accelerated pre-oligodendrocyte maturation into myelinating oligodendrocytes, evidenced by an increase in myelin-associated genes including MBP and MAG." (PMID 38200558, 2024). "At the gene level, chorioamnionitis decreased the expression of PDGFC and PDGFRA and increased the expression of MBP, MAG, and MOG, consistent with our finding of decreased MBP at the protein level." (PMID 38200558, 2024).
chronic respiratory failure (1 paper, 2024). "Here, we describe the case of a patient with positive anti-MAG antibodies presenting with clinical manifestations of DADS-M, including symmetric sensorimotor dysfunction of the distal extremities complicated by chronic respiratory failure." (PMID 38912071, 2024).
colorectal cancer (1 paper, 2017). A primary or metastatic malignant neoplasm that affects the colon or rectum. "In an attempt to understand the mechanism by which MAG-EPA mediates its antitumor effects in colorectal cancer cells, we determined whether this monoglyceride form of omega-3 modulates VEGFR and EGFR signaling pathways in tumor homogenates derived from control (untreated) and MAG-EPA-treated mice." (PMID 28869531, 2017).
dyslipidemia (1 paper, 2024). "The patient suffered from type 2 diabetes, moderate renal insufficiency, interstitial lung disease and dyslipidemia, had a history of acute autoimmune polyneuropathy with positive anti-myelin-associated-glycoprotein antibody and a positive Treponema Pallidum hemagglutination assay test." (PMID 39451612, 2024).
gastric disease (1 paper, 2023). "Alternatively, increased pH of the stomach acid as a result of gastric disease progression (i.e., NAG and MAG-IM) may have facilitated increased colonization of non-H. pylori species." (PMID 36907988, 2023).
Hallucinations (1 paper, 2019). Perceptions in a conscious and awake state that, in the absence of external stimuli, have qualities of real perception. "We hypothesised that the occipital cortex from AD patients with visual hallucinations would show evidence of reduced perfusion as measured by the MAG:PLP1 ratio in V2 and V3 compared to controls and to AD patients without visual hallucinations." (PMID 31511061, 2019).
hemorrhage (1 paper, 2025). Loss of blood from the vascular compartment to the exterior or into nonvascular body space as a result of rupture or severance of the blood vessels. "Additionally, triple immunostaining with NeuN, MBP, and MAG confirmed that knocking out Lcn2 in microglia effectively enhances neuronal myelin recovery at the hemorrhage site during the chronic phase of ICH in mice." (PMID 40225581, 2025).
hereditary cerebellar ataxia (1 paper, 2024). Cerebellar ataxia that is transmitted from parent to child. "MAG emerged as the primary candidate gene to cause HSP and frequently overlaps with hereditary cerebellar ataxia (HCA)." (PMID 39336794, 2024).
inflammatory disease of the skin (1 paper, 2013). "Psoriasis vulgaris is a common inflammatory disease of the skin, and myelin-associated glycoprotein-related neuropathy is a chronic sensory-predominant polyneuropathy." (PMID 23286283, 2013).
macroglobulinemia (1 paper, 2017). Macroglobulinemia is the presence of increased levels of macroglobulins in the circulating blood. "The Eighth International Workshop in Waldenström Macroglobulinemia consensus panel for the diagnosis and management of IgM-associated peripheral neuropathy in patients with MGUS recommends tailoring of the initial therapy on the basis of the presence (or not) of anti-MAG antibodies." (PMID 29399323, 2017).
migraine (1 paper, 2019). "Here we investigated a potential link between migraine and five key Nogo-type signaling genes: RTN4, OMGP, MAG, RTN4R and LINGO1, by screening 15 single nucleotide polymorphisms (SNPs) within these genes." (PMID 31861860, 2019).
neuromyelitis optica (1 paper, 2025). A rare inflammatory disease of the central nervous system characterized mainly by attacks of uni- or bilateral optic neuritis (ON) and acute myelitis. "A lumbar puncture was also performed, which showed a normal opening pressure with a negative oligoclonal IgG bands test, negative anti-myelin-associated glycoprotein antibody (MAG) test, and negative neuromyelitis optica/Aquaporin-4 (NMO) antibody test." (PMID 40821180, 2025).
non-small cell lung carcinoma (1 paper, 2017). A group of at least three distinct histological types of lung cancer, including non-small cell squamous cell carcinoma, adenocarcinoma, and large cell carcinoma. "For instance, magainin A (MAG A) and magainin G (MAG G) have been shown to have synergistic effects when used with chemotherapy against non-small cell lung cancer cell lines." (PMID 29081781, 2017).
osteosarcoma (1 paper, 2008). A usually aggressive malignant bone-forming mesenchymal neoplasm, predominantly affecting adolescents and young adults. "The deletion analysis of the MAG promoter revealed the induction of luciferase activity in Schwann cells but much less in rat osteosarcoma (ROS) cells." (PMID 18941509, 2008).
Parkinson’s (1 paper, 2022). "This study demonstrated an elevation in the production of anti-MAG IgM antibodies in PD patients, along with an activation of the humoral response against MAG in Parkinson’s patients." (PMID 35159390, 2022).
psoriatic arthritis (1 paper, 2013). Joint inflammation associated with psoriasis. "We diagnosed our patient with myelin-associated glycoprotein-related neuropathy associated with psoriatic arthritis." (PMID 23286283, 2013).
relapsing (1 paper, 2008). "Accordingly, in H-2b/smice we found markedly reduced levels of MAG in acute and even more pronounced in relapsing disease." (PMID 18541027, 2008).
Tremor (1 paper, 2009). An unintentional, oscillating to-and-fro muscle movement about a joint axis. "An example of this is the myelin-associated glycoprotein (MAG) gene that is deleted in one patient (case 123) and duplicated in another (case 124), whilst the knockout of its orthologous gene in mice leads to both abnormal axon morphology and tremors phenotypes." (PMID 19557186, 2009).
viral infection (1 paper, 2019). "MAG and EphA4 expression levels were assessed in the crushed sciatic nerve by immunochemistry and Western blotting at 28 days post-viral infection or siRNA interference." (PMID 31798398, 2019).
vitamin D deficiency (1 paper, 2012). A nutritional condition produced by a deficiency of VITAMIN D in the diet, insufficient production of vitamin D in the skin, inadequate absorption of vitamin D from the diet, or abnormal conversion of vitamin D to its bioactive metabolites. "Vitamin D deficiency was found in some autistic children and this deficiency may contribute to the induction of the production of serum anti-MAG auto-antibodies in these children." (PMID 22898564, 2012). "The results of this study may indicate that 25-hydroxy vitamin D deficiency may be a possible contributing factor to the increased frequency of serum anti-MAG auto-antibodies in some autistic children." (PMID 22898564, 2012).
peripheral neuropathy (26 papers, 2009 to 2025). A disorder affecting the peripheral nervous system. "One such complication is anti-Immunoglobulin M(IgM) Anti-Myelin Associated Glycoprotein (MAG) Peripheral Neuropathy, where IgM antibodies attack glycoproteins on myelin surrounding peripheral nerves, leading to demyelination." (PMID 39417016, 2024). "Peripheral neuropathy is another common complication, often related to the deposition of IgM or its interaction with myelin-associated glycoprotein." (PMID 39559629, 2024). "Peripheral neuropathy with antibodies to myelin-associated glycoprotein (MAG) is an autoimmune demyelinating disorder of the peripheral nervous system caused by pathogenic IgM recognizing the human natural killer-1 glycoepitope expressed on MAG." (PMID 38169815, 2023). "Anti-Myelin Associated Glycoprotein (anti-MAG) neurological involvement classically manifests as a peripheral neuropathy with prominent sensitive symptoms." (PMID 32397154, 2020). "Indeed, MAG-deficient mice, although showing a normal myelination process, later develop a peripheral neuropathy with myelin degeneration and neural cytoskeleton alteration with consequent reduction in axon caliber." (PMID 33498362, 2021). "Single-agent rituximab is the first option for patients with anti-MAG IgM peripheral neuropathy or anti-ganglioside antibodies, with ibrutinib being the most promising option in refractory patients." (PMID 34680279, 2021). "In this context, the patient was diagnosed with anti-MAG peripheral neuropathy related to the IgM MGUS." (PMID 34680279, 2021). "This process is seen in IgM-peripheral neuropathy, as the IgM binds directly to gangliosides or myelin glycoproteins (MAG)." (PMID 34680279, 2021). "Additionally, hexameric IgM may also be involved in other auto-immune phenomena related to monoclonal IgM, such as anti-MAG peripheral neuropathy that has been related to complement activation." (PMID 41280904, 2025). "In anti-myelin-associated glycoprotein IgM paraprotein-related peripheral neuropathy (anti-MAG PN), there is a lack of reliable biomarkers to select patients eligible for therapy and for evaluating treatment effects, both in routine practice and in clinical trials." (PMID 35157138, 2022). "Thus, anti-MAG peripheral neuropathy accounts for about 50% of IgM peripheral neuropathy." (PMID 34680279, 2021). "Indeed, pro-inflammatory cytokines are involved in the development of peripheral neuropathies in mice and humans, and MAG may protect nerve fibers by reducing local inflammation mediated by oxidative species." (PMID 31741707, 2019). "MAG is a common myelin antigen that is expressed both in the CNS and the PNS and is also an antigenic target in peripheral neuropathies." (PMID 33810144, 2021).
tumor (19 papers, 2007 to 2025). "High expression of PVR and MAG genes in U87-MG cells is associated with poor prognosis due to their role as cell adhesion molecules promoting tumor growth and metastasis." (PMID 40739397, 2025). "Further studies identified that myelin-associated glycoprotein (MAG) overexpressed by tumor-treated-SCs was responsible for this phenomenon." (PMID 39769484, 2024). "In addition, we not only studied the predictive performance of the risk model, but also explored the effect of MAG expression on the tumor immune microenvironment in DLBCL." (PMID 35468826, 2022). "In addition, the exposure of SCs to tumor cells elevates their expression of myelin-associated glycoprotein (MAG), which inhibits axonal growth and influences glia-axon interactions." (PMID 33015034, 2020). "According to literature reports, the interaction of Siglec-15 with its ligands CD44, MAG, and sialyl-Tn mediates immune escape in the tumor microenvironment, thus affecting the development of tumors." (PMID 40507880, 2025). "These symptoms are hypothesized to occur due to IgM deposition in nerves, direct tumor infiltration, and the presence of anti-MAG and anti-GM antibodies." (PMID 41040767, 2025). "Genes critical to oligodendroglial myelination, including myelin-associated glycoprotein (MAG), myelin basic protein (MBP), and myelin oligodendrocyte glycoprotein (MOG), showed significantly decreased expression in tumor tissue following 4-week treatment with the combination." (PMID 38319732, 2024). "In addition, recent studies have focused on the relationship between metabolism and survival: pan-cancer studies have indicated that tumor subtypes with different MAG expression patterns lead to significantly different survival." (PMID 35468826, 2022). "Indeed, MAG itself increases the immunosuppressive potential of MDSCs in a T cell inhibitory assay in a similar manner to that through which SCs are exposed to tumor cells." (PMID 33015034, 2020). "In a xenograft model established by subcutaneous inoculation of NCI-H157-S15 cells into BALB/c nude mice, these antibodies showed distinct tumor targeting and significant blockade of Siglec-15 interactions with CD44, MAG, sialyl-Tn, and LRR4C ligands." (PMID 40507880, 2025). "The oligodendrocyte marker genes OPALIN, MAG, and KLK6 are up-regulated in tumor cells and down-regulated in the periphery." (PMID 35327982, 2022). "To assess if demyelination occurred throughout the normal brain after treatment with the combination, we assessed MAG and MBP expression via IHC using both RA-055 xenograft tumors collected at endpoint and tumor naive C57BL/6J mice, treated with the combination for 4-weeks." (PMID 38319732, 2024). "Treatment decreased expression of MBP and MAG in RA-055 xenograft tissue in line with the UON-VIBE5 model, however, expression did not change in normal mouse brain tissues, suggestive of a tumor-specific effect." (PMID 38319732, 2024). "The migration of immune cells to tumor environment is the first step to exert their effects, therefore we selected the genes related to leukocyte migration, including IL-1β, ITGA4, ITGB2, ITGB7, CAV1, and MAG." (PMID 32358484, 2020). "Notably, the ability of S1, S5, and S6 for Siglec-15 to disrupt interactions with key ligands (CD44, MAG, sialyl-Tn, and LRR4C) suggests a dual mechanism of action: direct blockade of Siglec-15-mediated immunosuppressive signaling and potential modulation of ligand-dependent tumor-stroma crosstalk." (PMID 40507880, 2025). "In light of these genetic interactions, a growth advantage could be conferred to tumor cells that overexpress SHH through interaction with currently unknown growth promoting targets, while at the same time abrogating OLIG1 expression concomitant to MAG down-regulation." (PMID 17388669, 2007).
tumor (continued). "Therefore, this phenotypic difference could stem, in part, from lack or reduced MAG expression in OLIG1 negative tumors, which could facilitate detachment of tumor cells from the primary tumor mass." (PMID 17388669, 2007).
infection (12 papers, 2014 to 2026). The state of being infected such as from the introduction of a foreign agent such as serum, vaccine, antigenic substance or organism. "Cells were cultured for 4 days post infection to allow expression of shRNA sequences, and the role of MAG-Fc (20 μg/ml) against apoptosis was then tested." (PMID 26335717, 2015). "Furthermore, infection modestly reduced MAG and PLP levels by 17.4%, and 16.0%, respectively, compared to those from PBS-inoculated controls, corroborating the mRNA expression analysis." (PMID 37596606, 2023). "This notion is highly supported by our findings that αTAT1 downregulation is both temporally and spatially identical to α-tubulin acetylation changes downstream of MAG or CSPGs treatment, and that αTAT1 reconstitution by lentiviral-αTAT1 infection can overcome neurite growth inhibition." (PMID 29497702, 2018). "Furthermore, culture of sorted single cells isolated on day 7 after PR8-OVA infection showed significantly less expansion of mKO2+ cells compared with mAG+CD62Llo cells ex vivo." (PMID 25709008, 2015). "The MAG ECD was fused with transmembrane/intracellular domains of activating paired immunoglobulin-like receptor b (PILRb) in this system, followed by infection into murine T-cell hybridoma cells with a nuclear factor of activated T cells (NFAT)/GFP reporter gene." (PMID 36855057, 2023). "WB and IHC staining showed that, MAG, a myelin structural protein, was expressed at significantly higher levels in the sciatic nerve of Gnao1-NKD mice than in their controls, and GFP staining again revealed a strong infection efficiency of the virus in injected animals." (PMID 38331815, 2024). "Likewise, immunoblots performed on blocks of tissue isolated from mPFC, cerebellum, and hippocampus tissue of PBS- and IAV-inoculated mice indicated that infection did not alter abundance of MAG, MOG, or SOX10." (PMID 37596606, 2023). "HSV-1 uses several routes of entry to initiate infection of cells including HVEM (TNFRSF14), nectin-1, nectin-2, 3-O-sulfated heparan sulfate (3-OS-HS), paired immunoglobulin-like type 2 receptor (PILRα), non-muscle myosin heavy chain IIA (NMHC-IIA), and myelin-associated glycoprotein (MAG)." (PMID 37738264, 2023).
cancer (8 papers, 2010 to 2025). A tumor composed of atypical neoplastic, often pleomorphic cells that invade other tissues. "This process is mediated by specific adhesion molecules, such as Mucin 1 (MUC1) on cancer cells, binding to Myelin-Associated Glycoprotein (MAG) on nerves, and interactions involving NCAM1 and β1 integrin." (PMID 40909268, 2025). "Interestingly, another up-regulated gene in cancer cells grown with the CAFs, which contributes to cancer invasion is myelin-associated glycoprotein (MAG) that binds to the oncogenic glycoprotein MUC1." (PMID 22453032, 2012). "To assess the antitumoral potential of MAG, we used cellular models involving fibroblasts and cancer cells." (PMID 31741707, 2019). "Because the MAG gene up-regulation was found in cancer cells grown as a co-culture with the CAFs, the expression of MUC1 (which binds MAG) was examined immunohistochemically." (PMID 22453032, 2012). "For the purposes of the microarray data validation, we have randomly selected 3 of all the genes that may play the most important role in the cancer cells-CAFs interactions: PCDH19, DSP and MAG." (PMID 22453032, 2012).
neurological disorders (5 papers, 2005 to 2025). "Both signatures included a number of genes (MBP, MOBP, MAG, OLIG1, and OLIG2) previously found in glial cells, several of which have been linked to neurological diseases." (PMID 16168081, 2005). "As a label-free modality, it is applicable to most vertebrates, i.e., not limited to fluorescently-labeled transgenic mice, thus simplifying experimental designs for studying neurological disorders in models where OL markers, such as CNP and myelin-associated glycoprotein (MAG), are dysregulated." (PMID 31293394, 2019).
neurodegenerative disease (4 papers, 2022 to 2024). A disorder of the central nervous system characterized by gradual and progressive loss of neural tissue and neurologic function. "Lower PLP was associated with more severe CTE, but MAG and PLP did not correlate with other neurodegenerative disease pathologies." (PMID 36895961, 2023).